SNORD123 (small nucleolar RNA, C/D box 123)
Gene: Small nucleolar RNA gene on chromosome 5 (9,548,836 to 9,548,905, forward strand). Ensembl gene ENSG00000239112.
Gene Ontology:
Biological process: RNA processing
Cellular component: nucleolus
Homologues: Orthologues: chimpanzee SNORD123 (99% identical), macaque SNORD123 (99% identical), guinea pig SNORD123 (97% identical), mouse Snord123 (97% identical), rat Snord123 (97% identical), dog SNORD123 (93% identical), rabbit SNORD123 (93% identical), pig SNORD123 (91% identical).
Diseases named in the same sentence as SNORD123 in open-access papers:
SNORD123 is named in the same sentence as 3 diseases in open-access papers, as found by Europe PMC text mining. Sharing a sentence is not in itself a finding about the gene and the disease. The quoted sentences say what the papers report.
lung carcinoma (1 paper, 2019). "Although few studies have revealed in detail the potential biological function of SNORD123, a specific publication in 2012 confirmed that this snoRNA may regulate the hypermethylation status of functional CpG islands in specific tumor subgroups, such as colorectal and lung cancer." (PMID 31052553, 2019).
cancer (1 paper, 2019). A tumor composed of atypical neoplastic, often pleomorphic cells that invade other tissues. "Similar to SNORD123, SNORD19 has also been reported to have a different expression pattern in different tumor subtypes, implying its potential capacity for cancer subtyping." (PMID 31052553, 2019).
tumor (1 paper, 2019). "According to this rule, the high expression of U3 and low expression of SNORD123 and U94B may indicate that the potential tumor is LGG." (PMID 31052553, 2019).